OSBPL3 (oxysterol binding protein like 3)
Description:
Lipid transfer protein that mediates the non-vesicular transport of phosphoinositide 4-phosphate (1,2-diacyl-sn-glycero-3-phospho-(1D-myo-inositol 4-phosphate), or PI(4)P) at the plasma membrane (PM)/ endoplasmic reticulum (ER) contact sites. Extracts PI4P from the PM, in exchange for phosphatidylcholine. Can bind to the ER membrane protein VAPA and recruit VAPA to PM sites, thus linking these intracellular compartments. The ORP3-VAPA complex stimulates RRAS signaling which in turn attenuates integrin beta-1 (ITGB1) activation at the cell surface. With VAPA, may regulate ER morphology. Has a role in regulation of the actin cytoskeleton, cell polarity and cell adhesion. Binds to phosphoinositides with preference for PI(3,4)P2 and PI(3,4,5)P3. Also binds 25-hydroxycholesterol and cholesterol.
Synonyms: ORP-3; KIAA0704; ORP3; OSBP3
Tractability: Small molecule: a structure with a bound ligand is known. Antibody: UniProt places it where antibodies can reach, with high confidence; its Gene Ontology location is reachable by antibodies, with high confidence. PROTAC: ubiquitination databases record sites on it; its protein half-life has been measured.
Gene: Protein-coding gene on chromosome 7 (24,796,540 to 24,981,634, reverse strand). Ensembl gene ENSG00000070882.
Subcellular location: Endoplasmic reticulum membrane; Cytoplasm, cytosol; Cell membrane; Cell projection, filopodium tip; Nucleus membrane
Subcellular location (Human Protein Atlas): Cytosol; Nucleoli
Pathways (Reactome):
Metabolism: Synthesis of bile acids and bile salts
Gene Ontology:
Molecular function: cholesterol binding; lipid exchange activity; protein binding; sterol transfer activity; lipid binding
Biological process: regulation of focal adhesion assembly; bile acid biosynthetic process; intermembrane lipid transfer; sterol transport
Cellular component: cytosol; endoplasmic reticulum-plasma membrane contact site; membrane; nuclear membrane; nucleolus; perinuclear endoplasmic reticulum; plasma membrane; endoplasmic reticulum membrane; filopodium tip
Genetic constraint (gnomAD): Loss-of-function variants: 44 observed, 76.97 expected, observed/expected ratio (o/e) 0.57, 90% interval 0.45 to 0.74. The upper end of that interval is the gene's LOEUF score, 0.74, which puts it in group 3 of 6, group 1 being the genes least tolerant of losing a copy. Missense variants: 675 observed, 762.3 expected, observed/expected ratio (o/e) 0.89, 90% interval 0.83 to 0.94. Synonymous variants: 300 observed, 293.92 expected, observed/expected ratio (o/e) 1.02, 90% interval 0.93 to 1.12.
Homologues: Orthologues: macaque OSBPL3 (98% identical), chimpanzee OSBPL3 (97% identical), dog OSBPL3 (94% identical), pig OSBPL3 (93% identical), guinea pig OSBPL3 (92% identical), mouse Osbpl3 (91% identical), rabbit OSBPL3 (91% identical), rat Osbpl3 (91% identical), tropical clawed frog osbpl3 (70% identical), zebrafish osbpl3b (65% identical), zebrafish osbpl3a (52% identical). Paralogues in human: OSBPL6 (59% identical), OSBPL7 (49% identical), OSBPL1A (26% identical), OSBP2 (26% identical), OSBP (26% identical), OSBPL2 (19% identical), OSBPL5 (17% identical), OSBPL8 (17% identical), OSBPL10 (17% identical), OSBPL9 (16% identical), OSBPL11 (15% identical).
Diseases named in the same sentence as OSBPL3 in open-access papers:
OSBPL3 is named in the same sentence as 56 diseases in open-access papers, as found by Europe PMC text mining. Sharing a sentence is not in itself a finding about the gene and the disease. The quoted sentences say what the papers report.
colon carcinoma (7 papers, 2020 to 2023). "OSBPL3 was overexpressed in tumor tissues compared with normal tissues in almost all cancers evaluated, and high OSBPL3 expression was significantly associated with poor prognosis in colon cancer, pancreatic cancer, liver cancer, bladder cancer, and lung adenocarcinoma." (PMID 34584127, 2021). "But Xu’s study reported that colon tumor tissues had a lower expression of OSBPL3 than normal tissues and it is contrary to our findings." (PMID 37550605, 2023). "Interestingly, our experimental data showed that the higher the grade of colon cancer, the higher the level of OSBPL3 expression." (PMID 34738015, 2021). "The results showed that the expression levels of ACSL6, CYP19A1, LRP2, OSBPL3 and SLCO1A2 were considerably increased, while those of ACOX1, FABP4, PLAAT5, PPARGC1A and TNFAIP8L3 were decreased in colon cancer." (PMID 38045683, 2023).
colorectal cancer (6 papers, 2021 to 2025). A primary or metastatic malignant neoplasm that affects the colon or rectum. "Furthermore, OSBPL3 is generally considered to be an oncogene factor in colorectal cancer progression, acting through upregulation by HIF1A and activation of the RAS signaling pathway." (PMID 34738015, 2021). "For instance, the upregulation of OSBPL3 can promote colorectal cancer tumorigenesis, and OSBPL5 may become a potential indicator of diagnosing of prostate cancer." (PMID 34829830, 2021). "Recent transcriptome analyses from the perspective of pathology and clinical pathways have suggested that OSBPL3 is expressed and involved in the development of cancers, including colorectal cancer, pancreatic ductal adenocarcinoma, recurrent glioblastoma, and metastatic breast cancers." (PMID 34738015, 2021). "In colorectal cancer, six genes were positively correlated: ANLN, ACOT7, OSBPL3, SEC61G, DDX56, and TRIM10." (PMID 40765570, 2025).
breast carcinoma (4 papers, 2018 to 2025). "The expression level of OSBPL3 is significantly higher than the corresponding normal tissues in multiple tumor tissues except breast cancer." (PMID 34738015, 2021). "Additionally, OSBPL3 shows an enhanced phosphorylation level at S426, S251, and S273 loci within the pleckstrin homology domain in multiple tumors, such as breast cancer or lung adenocarcinoma." (PMID 34738015, 2021).
pancreatic cancer (4 papers, 2021 to 2026). "Indeed, OSBPL3 could further regulate integrin function and is upregulated in pancreatic cancer tissues." (PMID 34829830, 2021). "The data demonstrated that OSBPL3, OSBPL8, OSBPL10, and OSBPL11 were overexpressed in pancreatic cancer tissues." (PMID 34829830, 2021).
cervical cancer (3 papers, 2021 to 2025). A primary or metastatic malignant neoplasm involving the cervix. "Another study found that in cervical cancer patients, the expression level of OSBPL3 decreased due to miR-497/195 targeting those genes, which affected their overall survival." (PMID 41466006, 2025).
gastric cancer (3 papers, 2021 to 2023). A primary or metastatic malignant neoplasm involving the stomach. "In addition, transcriptome analyses showed that OSBPL3 is associated with tumorigenesis including colorectal, pancreatic ductal, pancreatic head, gastric cancer and metastatic breast cancer." (PMID 37550605, 2023). "In gastric cancer, the role of OSBPL3 has already been described: it promotes tumor growth by enhancing R-Ras/Akt signaling." (PMID 37370678, 2023).
glioma (3 papers, 2020 to 2023). A benign or malignant brain and spinal cord tumor that arises from glial cells (astrocytes, oligodendrocytes, ependymal cells). "In our study, OSBPL3, which regulates lipid metabolism, is known to control glioma aggressiveness and appeared to be involved in proliferation through the Akt pathway in ODs." (PMID 37370678, 2023).
liver cancer (3 papers, 2021 to 2023). An epithelial or non-epithelial malignant neoplasm that arises from the liver. "Then we performed ROC analysis to evaluate the diagnostic potency of OSBPL3 in liver cancer which demonstrated that OSBPL3 was a strong predictor (AUC = 0.921, CI = 0.883–0.959)." (PMID 36918840, 2023). "The ROC analysis identified OSBPL3 was a diagnostic factor of liver cancer." (PMID 36918840, 2023). "Initially, the mRNA expression of OSBPL3 in liver cancer cell lines were detected which displayed that OSBPL3 was highly expressed in PLC/PRF/5 compared to the other 5 liver cancer cell lines." (PMID 36918840, 2023). "CCK-8, cell cycle, apoptosis, transwell assays, real time qPCR (RT-qPCR), and western blot assays were conducted to investigate the biologic functions of OSBPL3 in liver cancer cells." (PMID 36918840, 2023). "Functionally, knocking down OSBPL3 reduced liver cancer cell viability, induced a G2/M cell cycle arrest, promoted apoptosis, and restrained cell migration." (PMID 36918840, 2023). "First, expression validation of OSBPL3 in liver cancer was conducted by analyzing four cohorts of GEO datasets which demonstrated that OSBPL3 mRNA was drastically increased in tumor samples." (PMID 36918840, 2023). "Given our findings that OSBPL3 is overexpressed and prognostic in liver cancer, we hypothesized that OSBPL3 may play a crucial role in liver cancer development." (PMID 36918840, 2023). "Immunohistochemistry (IHC) was applied to validate the expression of OSBPL3 in liver cancer." (PMID 36918840, 2023). "Moreover, 10 local liver cancer specimens were involved to validate the expression of OSBPL3 via immunohistochemistry (IHC) assay." (PMID 36918840, 2023). "Notably, OSBPL3 appeared as the only gene related to both OS and DSS in these two lasso models, indicating that OSBPL3 was a prognostic factor of liver cancer." (PMID 36918840, 2023). "Especially, we found OSBPL3 was overexpressed and a prognostic factor in liver cancer." (PMID 36918840, 2023). "Finally, CCK-8, cell cycle, apoptosis, transwell assays, real time qPCR (RT-qPCR), and western blot assays were conducted to explore the function of OSBPL3 in liver cancer cells." (PMID 36918840, 2023). "The subsequent functional experiments verified that knocking down OSBPL3 led to cell proliferation inhibition by inducing a G2/M cell cycle arrest and apoptosis and restrained cell migration.These results implies that OSBPL3 might be a prognostic marker and regulator of liver cancer." (PMID 36918840, 2023). "The mRNA of OSBPL2, OSBPL3, and OSBPL8 were highly expressed while OSBPL6 was lowly expressed in liver cancer samples compared with normal samples." (PMID 36918840, 2023). "In order to evaluate the prognostic of OSBPLs in liver cancer, OS and DSS related lasso models were constructed which exerted that OSBPL3 was a key prognostic factor to both OS and DSS." (PMID 36918840, 2023). "Taken together, these results imply that OSBPL2, OSBPL3, and OSBPL6 were potentially involved in liver cancer progression." (PMID 36918840, 2023). "Notably, OSBPL3 was identified correlated to overall survival (OS) and disease specific survival (DSS) in liver cancer." (PMID 36918840, 2023).
lung carcinoma (3 papers, 2021 to 2023). "Overexpression of OSBPL3 has also been found and associated with poor prognoses in other tumors, such as colorectal, pancreatic, liver, bladder, and lung cancers, in the TCGA database." (PMID 37370678, 2023). "Surprisingly, OSBPL3 was also overexpressed and associated with poor prognosis in colorectal, pancreatic, liver, bladder, and lung cancers in the TCGA database." (PMID 34584127, 2021).
lymph node metastasis (3 papers, 2020 to 2022). "Because depth of tumor invasion, lymph node metastasis, and distant metastasis are highly linked to pathological stage, we selected high OSBPL3 expression and pathological stage to evaluate in the multivariate analysis." (PMID 34584127, 2021). "The clinicopathological factors identified as prognostic factors in the univariate analyses were high OSBPL3 expression, depth of tumor invasion, lymph node metastasis, distant metastasis, and pathological stage." (PMID 34584127, 2021).
glioblastoma (2 papers, 2021 to 2023). The most malignant astrocytic tumor (WHO grade IV). "In the BELOB trial, we note that OSBPL3 expression was related to a response benefit to dual therapy combining bevacizumab and CCNU in patients followed for recurrent glioblastoma." (PMID 37370678, 2023).
metabolic dysfunction-associated steatotic liver disease (2 papers, 2020 to 2025). Metabolic dysfunction-associated steatotic liver disease (MASLD, formerly known as nonalcoholic fatty liver disease or NAFLD) is a type of liver disease that is not caused by alcohol. "OSBPL3 is vital for fatty liver disease, but its immune mechanisms in metabolic dysfunction-associated steatotic liver disease (MASLD) are unclear." (PMID 41466006, 2025).
pancreatic ductal adenocarcinoma (2 papers, 2017 to 2023). An infiltrating adenocarcinoma that arises from the epithelial cells of the pancreas. "In the present study, we determined the feasibility of three genes (ERO1A, OSBPL3 and IFI44L) working as potential biomarkers in pancreatic ductal adenocarcinoma (PDAC)." (PMID 28881752, 2017).
Alzheimer disease (1 paper, 2025). A progressive, neurodegenerative disease characterized by loss of function and death of nerve cells in several areas of the brain leading to loss of cognitive function such as memory and language. "Additionally, GSEA revealed that OSBPL3 was notably enriched in pathways related to “Alzheimers disease,” “Huntingtons disease,” “oxidative phosphorylation,” and “Parkinsons disease”." (PMID 41466006, 2025).
depressive disorder (1 paper, 2023). A melancholy feeling of sadness and despair. "Gene-trait association was mostly seen with SCZ, additionally, TRANK1, ADD3 and CDAN1 were TWAS positive for BD, OSBPL3 for depressive disorder and CACNA1G for ADHD." (PMID 38104115, 2023).
esophageal adenocarcinoma (1 paper, 2021). A malignant tumor with glandular differentiation arising predominantly from Barrett mucosa in the lower third of the esophagus. "The highest mutation frequency of OSBPL3 (>6%) appears for patients with uterine corpus endometrial carcinoma and the amplification (an alteration frequency of ∼5%) appears for the esophageal adenocarcinoma." (PMID 34738015, 2021).
low grade glioma (1 paper, 2021). A grade I or grade II glioma arising from the central nervous system. "High expression level of OSBPL3 correlates with poor prognosis of OS (overall survival) for LGG (low-grade glioma), MESO, THYM, and UVM (uveal melanoma) cancers and DFS (disease-free survival) for GBM, LGG, LUAD, and UVM cancers (all p < 0.05)." (PMID 34738015, 2021).
skin cutaneous melanoma (1 paper, 2021). "We observed X676_splice/V676G alteration in the oxysterol domain and frequent mutations of OSBPL3 involve cell survival in skin cutaneous melanoma." (PMID 34738015, 2021).
tumor (16 papers, 2017 to 2026). "OSBPL3 was found to be significantly overexpressed in CRC tumor tissues and was associated with worse progression-free survival and overall survival in patients." (PMID 36517805, 2022). "OSBPL3 is overexpressed in a variety of malignancies and is closely associated with tumor growth and metastasis." (PMID 36517805, 2022). "These clinical data indicate that high expression of OSBPL3 is strongly associated with tumor progression and poor prognosis in GC patients." (PMID 34584127, 2021). "OSBPL3 is highly expressed in major subtypes of cancers, distinctly associated with the prognosis of tumor patients." (PMID 34738015, 2021). "We also first presented that the expression of OSBPL3 was associated with tumor mutational burden (TMB) in nine cancer types." (PMID 34738015, 2021). "We also analyzed the correlation between OSBPL3 expression and tumor mutational burden (TMB)/microsatellite instability (MSI) across diverse tumors from TCGA." (PMID 34738015, 2021). "In the clinicopathological analysis, high OSBPL3 expression was significantly associated with the depth of tumor invasion, lymph node metastasis, stage III/IV, well or moderately differentiated adenocarcinoma, and age (Fisher’s exact test, p < 0.05) based on the GSE15459 dataset." (PMID 34584127, 2021). "In the current study, we explored the expression of OSBPL3 in 15 types of tumor cells and their para-cancerous tissues, revealing that OSBPL3 has a higher expression in most tumors." (PMID 37550605, 2023). "Oxysterol binding protein-like 3 (OSBPL3), also known as oxysterol binding protein-related protein 3 (ORP3), is a bona fide tumour suppressor gene." (PMID 38045683, 2023). "It was validated that knockout of OSBPL3 is likely to promote tumour progression and induce aneuploidy, and the mRNA level of OSBPL3 in cancer is closely associated with patient survival." (PMID 38045683, 2023). "At the same time, there were different overall survival curves between the OSBPL3 high expression and low expression cohorts in terms of tumor stage and weight difference." (PMID 37550605, 2023). "The results showed that the expression of OSBPL3 in tumor tissues was negatively correlated with the degree of tumor differentiation." (PMID 36517805, 2022). "Significant differences in OSBPL3 immunohistochemical scores were found in normal paracancerous tissues, highly differentiated tumor tissues, and poorly differentiated tumor tissues (P < 0.001), with increasing intensity of expression in ascending order." (PMID 36517805, 2022). "We first analyzed OSBPL3 mRNA expression using RT-qPCR in 109 paired tumor and normal tissues from GC patients at our hospital." (PMID 34584127, 2021). "In conclusion, our study demonstrates that OSBPL3 is a novel driver gene that promotes tumor growth in part by promoting R-Ras/Akt signaling in GC cells." (PMID 34584127, 2021). "In this study, we identified OSBPL3 on chromosome 7 as a novel driver gene that facilitates tumor growth by promoting R-Ras/Akt signaling in GC." (PMID 34584127, 2021). "As a result, we found that clinicopathological parameters and the value of OSBPL3 expression were significantly correlated with tumor stages in PDAC." (PMID 34829830, 2021). "We also first integrated the correlation between OSBPL3 expression and the tumor microenvironment including immune infiltration and stromal cells, immune-related cells, and immune checkpoint inhibitors (ICIs) in a variety of tumors." (PMID 34738015, 2021). "We also compared the expression of OSBPL3 between the tumor tissues from TCGA and the normal tissues from the GTEx dataset." (PMID 34738015, 2021). "OSBPL3 overexpression was found to be involved in cell adhesion and interaction with R-Ras signaling, which promots tumor progression." (PMID 34829830, 2021). "We found that OSBPL3-knockdown decreased tumor growth and inhibited cell cycle progression at the G1 and S phases." (PMID 34584127, 2021).